HOXA9 (homeobox A9)
Diseases named in the same sentence as HOXA9 in open-access papers (continued):
Sharing a sentence is not in itself a finding about the gene and the disease.
leukemia (continued). "For example, NUP98-HOXA9, a chimera generated by fusion between the DNA-binding domain of HOXA9 (a homeodomain-containing TF) and the FG-repeats-containing segment of NUP98, is associated with development of leukemias." (PMID 36821650, 2023). "C/EBPα was identified as a key collaborator that is enriched at HOXA9 binding sites, and is critical for maintaining proliferation in vitro, and directly contributes to severity of Hoxa9-driven leukemia in vivo." (PMID 36969082, 2023). "Considering the transcription factor HOXA9 is an oncogene and critical to the survival of MLL-r leukemia cells, exploring its direct downstream targets promises to provide insights into the HOXA9 regulome and to identify additional therapeutic targets." (PMID 38016946, 2023). "In these murine models, the cooperation between BCR::ABL and the NUP98/HOXA9 gives rise to very aggressive leukemia in mice similar to acute leukemia." (PMID 37174060, 2023). "JMJD1C regulates aberrant metabolic processes in acute myeloid leukemia, contributes to MLL-AF9/HOXA9-mediated self-renewal of leukemia stem cells, and suppresses leukemia cell growth by catalyzing H3K9 demethylation." (PMID 37759870, 2023). "Numerous studies have suggested that dysregulation of HOXA9 is a dominant driver in the pathogenesis of MLL-r leukemia." (PMID 38016946, 2023). "HOXA9 overexpression in both colorectal cancer and leukemia is another example of the effects of HOX gene dysregulation and is the focus of our current study." (PMID 35743243, 2022). "HOXA9 is a common driver of leukemia, one of the strongest predictors of survival in AML patients, and a transcriptional addiction in KMT2Ar AML." (PMID 35301220, 2022). "Selective drugs developed to restrain the proliferation of MLL-r leukemia cells through inhibiting DOT1L due to the ability of inducing the hyperexpression of HOXA9 and MEIS1." (PMID 36376832, 2022). "The overexpression of HOXA9 results in increased expression of these oncogenes, which in turn results in leukemia." (PMID 35743243, 2022). "In fact, Hoxa9/Meis1 combination is one of the most potent AML-inducing oncogenes that induce the fastest occurrence of leukaemia." (PMID 36285442, 2022). "Compound 1-mediated ENL depletion significantly suppressed aberrant gene signatures in MLL1-r leukemia, including reduced expression of several characteristic genes (e.g., HoxA9 and Myc)." (PMID 35395864, 2022). "Intriguingly, IRX1-positive leukemia blasts emerged only from HSCs or MPPs, whereas HOXA9-positive blasts emerged from all four HSPC compartments." (PMID 36042201, 2022). "Given that the interaction of menin and KMT2A protein is essential in initiating the oncogenesis of HOXA9-driven leukemia, menin-KMT2A inhibitors are promising molecular-targeting agents applicable to a considerable proportion of AML patients." (PMID 35682627, 2022). "DOT1L methyltransferase inhibitors increase differentiation of MLLr leukemia cells and decrease proliferation, global H3K79me, and expression of HOXA9 and MEIS1." (PMID 35712672, 2022). "Hoxa9/Meis1 combination is among the most potent AML-inducing oncogenes that induce the fastest occurrence of leukaemia in mice." (PMID 36285442, 2022). "HOXA9, HOXA10, and HOXA7 are induced by MLL-AF4 and HOXA9 is required for MLL-rearranged leukemia survival." (PMID 34321607, 2022). "We previously found that MSI2 maintains MLL-leukemia self-renewal programs by retaining the translation of HOXA9, c-MYC, MYB, and IKZF218,31." (PMID 36167829, 2022). "DOT1L, however, is dispensable for BCR-ABL, E2A-HLF, E2A-PBX2 leukemias, and leukemia generated by ectopic retroviral overexpression of HOXA9/MEIS1." (PMID 35712672, 2022).
leukemia (continued). "To dissect the underlying mechanisms of the induced anti-leukemia effect and confirm the disruption of DOT1L recruitment to MLL target gene loci Hoxa9 and Meis1, we performed a chromatin immunoprecipitation coupled with qPCR (ChIP-qPCR)." (PMID 33562706, 2021). "Expression of HIV integrase in MLL-r leukemia cells suppressed the expression of HoxA9 in a dose-dependent manner and exerted antiproliferative activity." (PMID 33823889, 2021). "HOXA9 did not induce leukemia within 200 days either, suggesting that the HOXA9 high signature alone is also insufficient to induce leukemia." (PMID 34310280, 2021). "The combined expression of MYC/HOXA9 or MYC/MEIS1 induced leukemia in 38% and 18% of recipient mice, respectively, indicating a synergy of MYC with HOXA9 and MEIS1." (PMID 34310280, 2021). "The aberrant methylation of H3K79 by DOT1L would enhance the expression of leukemogenic genes homeobox A9 (HOXA9) and Meis Homeobox 1 (MEIS1), driving the pathogenic of mixed lineage leukemia (MLL) rearranged leukemia." (PMID 34425876, 2021). "Several generations of improved inhibitors have demonstrated specific inhibition of leukemia cell growth in vitro, induction of differentiation as well as downregulation of both HOXA9 and MEIS1 expression." (PMID 33542482, 2021). "DOT1L inhibitors are recognized as potential therapeutics for MLL leukemias, which also have high HOXA9 expression." (PMID 34202641, 2021). "MN1-driven leukemia is characterized by a CMP-like gene expression program that includes high expression of Hoxa9 and Meis1, known target genes of Kmt2a-fusion proteins but also of wild type Kmt2a." (PMID 33542482, 2021). "In concordance with our findings in the human cell line models, we found an increase in total protein expression and plasma membrane receptor expression in the murine CALM-AF10 leukemia cells relative to the Hoxa9-Meis1 translocated cells." (PMID 35070954, 2021). "DOT1L methyltransferase activity is critical to MLL-r leukemia and is recruited on DNA where it induces hyperexpression of HOXA9 and MEIS1." (PMID 34698191, 2021). "The combinational overexpression of Hoxa9 and Meis1 leads to a massive acceleration of leukemia development." (PMID 34150668, 2021). "MLL fusion- and HOXA9/MEIS1-transduced cells, which are capable of inducing leukemia in vivo, expressed Myc 20–100% more than HOXA9-ICs." (PMID 34310280, 2021). "For example, the missing target gene HOXA9 had elevated H3K4me3 scores in a small fraction of 1° MPAL-1 leukemia cells (~15%)." (PMID 34663924, 2021). "Next, compound 1 was tested for its ability to change expression of characteristic MLL-r leukemia genes HoxA9, Meis1 and Myc." (PMID 34373735, 2021). "Because there is a correlation between the expression levels of HOX proteins and the sensitivity to BCL2 inhibitor in AML patient samples, the aberrant expression of HOXA9 is the potential mechanism for BCL2-dependence of MLL leukemia." (PMID 34310280, 2021). "HOXA9-dependent leukemia have been found to be influenced by the activity of the TALE transcription factors PBX and MEIS." (PMID 34383740, 2021). "Another mouse study showed that wild-type CEBPA is required for KMT2A-MLLT1 driven leukemia through activation of Hoxa9/Meis1." (PMID 34944812, 2021). "Currently, it is well recognized that HoxA9 expression alone is only weakly oncogenic in mouse leukemia models and usually requires a second “hit”, the overexpression of Meis1." (PMID 34698191, 2021). "SEC is essential for expression of characteristic genes of MLL-r leukemia (e.g., HoxA9 and Meis1) as well as leukemia transformation." (PMID 33823889, 2021). "Menin is also required for MLL1-r leukemia, as conditional knockout of Menin inhibited MLL1-AF9 mediated leukemia transformation and suppressed expression of HoxA9, a characteristic gene for the leukemia." (PMID 33823889, 2021).
leukemia (continued). "C/EBPα−/− mice do not develop myeloid leukaemia even upon expression of Bcr-abl, and C/EBPα is required for the development of leukaemia in other models (MLL-fusion or Hoxa9/Meis1-induced leukaemia)." (PMID 34226527, 2021). "Enzymatically inactive KDM3C intensifies the aggressive phenotype of HOXA9 leukemia in mice similar to the wt protein." (PMID 34944554, 2021). "The combined expression of BCL2 with MYC induced leukemia in vivo with a penetrance similar to that with the MYC/HOXA9 combination, in accord with previous reports." (PMID 34310280, 2021). "Another observation made in mammalian leukemia models is the ability of TALE co-factors to accelerate AML onset when co-expressed along with HOXA9." (PMID 34383740, 2021). "Formation of SEC is required for expression of characteristic genes of MLL1-r leukemia (e.g., HoxA9 and Meis1) as well as leukemia transformation." (PMID 33823889, 2021). "As expected, the group of genes we identified as the most frequent KMT2A fusion targets across our collection of samples included several genes that are known to be required for KMT2Ar leukemia, including HOXA9, MEIS1, MEF2C, MBNL1 and JMJD1C25–29." (PMID 34663924, 2021). "RUNX1 S291fs/Ezh2 promotes MDS development by activating inflammatory cytokine responses but attenuates leukemia development via PRC1 mediated repression of Hoxa9." (PMID 34944812, 2021). "Meis1–3, Pbx1–3, and Hoxa9 are upregulated in thymoma, pancreatic adenocarcinoma, glioma, glioblastoma, and leukemia/lymphoma when compared to healthy tissue." (PMID 33402862, 2020). "Previous studies have shown that DOT1L and ENL positively regulate HOXA9 expression in MLLr leukemia via direct occupancy on HOXA9’s promoter." (PMID 33001025, 2020). "Later, TET1 was verified to promote cell proliferation and induce leukemia by activating the Hoxa9/Meis1/Pbx3 signaling pathway." (PMID 32014008, 2020). "Remarkably, as an important regulatory transcription factor in MLL leukemia, HOXA9 is reported to rewire leukemia-specific enhancers." (PMID 33143730, 2020). "It has been found that Meis1/Hoxa9 deregulation has an important function in the progression of leukemia." (PMID 33402862, 2020). "Collectively, the HOXA9 reporter facilitated the functional interrogation of the HOXA9 regulome and has advanced our understanding of the molecular regulation network in HOXA9-driven leukemia." (PMID 33001025, 2020). "Although our study identified the regulatory function of USF1/USF2 on HOXA9 maintenance and leukemia cell survival in MLLr B-ALL and AML cell lines, other HOXA9-independent functions of USF1/2 cannot be excluded and requires further studies." (PMID 33001025, 2020). "Increased Suv39h1 expression led to the inactivation of Hoxb13 and Six1, as well as reversion of Hoxa9/Meis1 downstream target genes, which in turn decelerated leukemia progression." (PMID 33037410, 2020). "The non-Normal prognostic marker genes in AML were also enriched for an oncogenic signature based on human leukemia cells from a HOXA9 knockdown." (PMID 33371881, 2020). "IKZF2 is recently found to drive leukemia stem cell renewal and inhibit myeloid differentiation, by regulating HOXA9 and CEBP." (PMID 32571260, 2020). "Forced expression of HOXA9 enforces self-renewal, impairs myeloid differentiation of murine marrow progenitors, and ultimately leads to late onset of leukemia transformation, which is accelerated by co-expression with interacting partner protein MEIS1." (PMID 33001025, 2020). "Compared to levels in Hoxa9/Meis1 leukemias, endogenous Hoxa9 and Hoxa10 were considerably elevated in SQSTM1-NUP214 leukemias, whereas the levels of Hoxa3, Hoxa5, Hoxa7, Hoxa11 and Meis1 were comparable in Hoxa9/Meis1 and SQSTM1-NUP214 leukemias." (PMID 32343715, 2020). "HOXA9 overexpression not only predicts poor diagnosis and outcome but also plays a critical role in leukemia transformation and maintenance." (PMID 33001025, 2020).
leukemia (continued). "Cut and Run analysis revealed the direct occupancy of USF2 at HOXA9 promoter in MLLr leukemia cells." (PMID 33001025, 2020). "Here, we focus on HOXA9, the aberrant expression of which is one of the most significant features in the most aggressive human leukemias." (PMID 33001025, 2020). "Other studies have supported a role of Meis1 and HoxA9 in cooperation with IDH1 or IDH2 mutant to drive leukemia development in mouse models." (PMID 32859092, 2020). "By utilizing the reporter and CRISPR/Cas9 screens, we identified transcription factors controlling HOXA9 expression, including a novel regulator, USF2, whose depletion significantly down-regulated HOXA9 expression and impaired MLLr leukemia cell proliferation." (PMID 33001025, 2020). "In certain leukemia subtypes, this regulatory switch fails and HOXA9 is maintained at high levels to promote leukemogenesis." (PMID 33001025, 2020). "Next, primary Hoxa9/Meis1 or MLL-AF9 leukemia cells were generated and transplanted to second recipient mice." (PMID 32039742, 2020). "Mutant IDH1 alone was unable to transform hematopoietic cells, but consistently accelerated leukemia development induced by HoxA9." (PMID 32859092, 2020). "The oncogenic function of HOXA9 was first assessed in human acute myeloid leukemia (AML), particularly in the mixed-phenotype associated lineage leukemia (MPAL) subtype." (PMID 31213012, 2019). "Similar to HOXA9, HOXA11 has been implicated in leukemia development, exemplified by a patient with juvenile myelomonocytic leukemia (JMML) carrying a NUP98-HOXA11 fusion gene." (PMID 31426381, 2019). "Changes in gene expression following Bcor mutation in the non-transformed and malignant settings were significantly correlated, with key TFs Hoxa7, Hoxa9 and Tal1 also upregulated in the context of leukaemia." (PMID 30902969, 2019). "Whilst several studies indicate a need for Hoxa expression, primarily Hoxa9, in the establishment of MLLr leukemia their absolute requirement for disease progression and maintenance is less clear." (PMID 31861091, 2019). "This translocation defines a leukemia subtype closely related to MLL-r leukemia, and is driven by shared mechanisms such as upregulation of the leukemogenic HOXA9/MEIS1 pathway." (PMID 30670779, 2019). "We showed that the group of sensitive MLL-r leukemia cells is characterized by a particular gene expression profile (low HOXA9, MEIS1, and CMYC mRNA levels) and low levels of MEIS1/HIF1α protein expression." (PMID 30670779, 2019). "HOXA9 over-expression in progenitor cells, therefore, leads to significant enhancer reorganizations with prominent emergence of leukemia-specific de novo enhancers." (PMID 31213012, 2019). "A previous study has shown that HOXA9 contributes to the proliferation, apoptosis, and differentiation processes of leukemia." (PMID 31080363, 2019). "Sustained expression of HOXA9 and MEIS1 in hematopoietic progenitors causes leukemia in mouse models, suggesting that these two genes are strong drivers of leukemogenesis." (PMID 30693017, 2018). "MLL-r leukemia cells express a subset of genes including HOXA9 and MEIS1 whose expression is normally confined to immature hematopoietic cells such as hematopoietic stem cells (HSCs) (hereafter we refer to as HSC program genes)." (PMID 30693017, 2018). "HOXA9 is also critical to maintain stem cell self-renewal and avoid aging of normal hematopoietic stem cells and leukemia stem cells." (PMID 29662084, 2018). "In vivo analyses, FOXC1 significantly accelerated the onset of symptomatic leukemia by collaborating with HOXA9." (PMID 29552326, 2018). "Cells with this immunophenotype are enriched for leukemia-initiating activity in Hoxa9/Meis1 murine leukemias." (PMID 29346763, 2018). "Gene set enrichment analysis (GSEA) confirmed that co-expression of IRX3 with Hoxa9 led to repression of a mature myeloid lineage program in KIT+Gr1+ leukemia cells, in keeping with morphologic analysis." (PMID 29346763, 2018).
leukemia (continued). "Hoxa9/IRX3 AML cells induced leukemias in secondarily transplanted recipients, and high-level IRX3 expression was readily detected in Hoxa9/IRX3 AML BM cells." (PMID 29346763, 2018). "It was shown to be an efficient inhibitor of MLL1 activity leading to a reduction of the expression of MLL1 target genes, such as HoxA9 and Meis1, in leukemia cell lines." (PMID 28182322, 2017). "We found that the combination of Hoxa9 and hSYK significantly increased the aggressiveness of the leukemias compared with Hoxa9 alone (median of 38.5 versus 103.5 days; p < 0.001), with a median survival remarkably similar to that of Hoxa9/Meis1 (39 days)." (PMID 28399410, 2017). "When transplanted into irradiated recipient mice, cells transduced with Hoxa9 (H) or Hoxa9/Meis1 (H/M) gave rise to leukemia resulting in a median overall survival of 114 and 41 days, respectively (p < 0.001)." (PMID 28399410, 2017). "Our orthogonal treatment results, based on both shRNA-mediated knockdown and pharmacological inhibition of Syk, showed that Hoxa9/Meis1-transformed leukemias were clearly more sensitive to Syk inhibition than Hoxa9-transformed leukemias." (PMID 28399410, 2017). "For example, miR-196b can target either tumour suppressor, FAS or oncogene, HOXA9/MEIS1 in leukaemia." (PMID 28458781, 2017). "These leukemia cells also displayed a similar lineage marker expression profile to that of Hoxa9+BCR/ABL and Hoxa10+BCR/ABL leukemia cells and were transplantable." (PMID 29228732, 2017). "The DOT1L protein is essential for the growth of MLL-rearranged leukemia cells and exerts its effect by maintaining active transcription of Hoxa9 and Meis1." (PMID 28231254, 2017). "In the context of Hoxa9 overexpression, Syk signaling induces Meis1, recapitulating several leukemogenic features of Hoxa9/Meis1-driven leukemia." (PMID 28399410, 2017). "In MLL-r leukemias, HOXA9 and its dimerization partner MEIS1 are the most well-characterized direct targets, which in turn can replace MLL-fusion proteins in overexpression experiments." (PMID 28974232, 2017). "Similar to leukemias induced by Hoxa9+BCR/ABL, these leukemias also are characterized by expansion and infiltration of myeloid blasts into the bone marrow, spleen, and liver." (PMID 29228732, 2017). "We next sought to characterize the functional consequences of Syk overexpression in the context of Hoxa9-driven leukemias." (PMID 28399410, 2017). "More biological studies demonstrated that LSD1 inhibitors 1 and 2 were able to downregulate the expression of leukemia-relevant genes HoxA9 and Meis1, induce apoptosis, and differentiation." (PMID 26970896, 2016). "Indirect evidence for a role of a hyperactivated HOXA9/MEIS1 pathway in MLL-r leukemia also comes forward from several gene expression studies in patients with MLL-r leukemia." (PMID 27317766, 2016). "This leads to aberrant H3K79 methylation at MLL target gene loci, causing dysregulated gene expression (e.g., overexpression of HoxA9 and Meis1) and eventually initiation of the leukemia." (PMID 26970896, 2016). "Similar to the MLL-GAS7 studies, there was strong pressure on select leukemia clones to escape from Prmt1 knockdown as indicated by their re-expression of Prmt1, and Hoxa9 in the leukemic mice received MOZ-TIF2 Prmt1 knockdown cells." (PMID 26766589, 2016). "Although the functions of all resultant fusion proteins have not been fully characterized, some commonalities exist, such as the up-regulation of downstream genes, Hoxa9 and Meis1, which in combination can induce aggressive leukemia in recipient mice." (PMID 27007052, 2016). "Similar to Prmt1 in vivo knockdown data, the few leukemias from the mice that received Kdm4c-knockdown cells actually re-expressed high levels of Kdm4c and Hoxa9, indicating a strong growth disadvantage of Kdm4c knockdown leukemia cells." (PMID 26766589, 2016).